BCL2 (BCL2 apoptosis regulator)
Diseases named in the same sentence as BCL2 in open-access papers (continued):
Sharing a sentence is not in itself a finding about the gene and the disease.
cancer (continued). "However, cancer cells will induce the expression of certain antiapoptotic proteins like Bcl-2 located in MAM sites to decrease the transfer of calcium into mitochondria upon cisplatin treatment." (PMID 35296653, 2022). "Therefore, it is of interest to explore new possible BH3 mimetics and to test them in the combination with known Bcl-2 proteins inhibitors or other cancer treatments to achieve possible synergy." (PMID 36267274, 2022). "Additionally, t-DARPP promotes cancer cell survival in the presence of trastuzumab by stimulating elevated levels of the anti-apoptosis protein Bcl-2, which leads to increased phosphorylation of AKT." (PMID 34675407, 2022). "It should also be considered that CDK6 is also present in the “regulation of cell differentiation” pathway, as long as Bcl2 is included not only in “negative regulation of apoptotic processing” but also in “regulation of cell differentiation” and “pathway in cancer”." (PMID 36498866, 2022). "PD may trigger apoptosis by raising the Bax/Bcl-2 ratio and decreasing Wnt/catenin signaling to kill cancer cells." (PMID 36364001, 2022). "The increasing of BCL2 as an anti-apoptotic factor in many cancers could be a promising target to combat malignant cells." (PMID 35879400, 2022). "However, such stress signals can be overcome by cancer cells overexpressing anti-apoptotic proteins, especially those of the BCL-2 (B-cell lymphoma-2) family." (PMID 36291779, 2022). "For example, the BCL-2 protein, which is anti-apoptotic, is highly upregulated in many cancers." (PMID 35563454, 2022). "It would be interesting to investigate whether the mechanism of resistance to PRMT5-targeted therapies mediated by the oncogenic axis, MSI2/c-MYC/BCL-2, could be extrapolated to the other cancers." (PMID 36167829, 2022). "Although this may seem initially counter-intuitive, precedence for increased apoptotic priming, correlating with high anti-apoptotic BCL-2 levels, is evident in various cancers." (PMID 35447090, 2022). "Interestingly, co-culturing CEVs with T cells resulted in elevated expression of BAX (proapoptotic marker) and decline in expression of BCL-2/BCL-XL (anti-apoptotic markers) indicating cancer mediated T cell suppression." (PMID 35517798, 2022). "By comparison, berberine showed a role in the inhibition of cancer cell viability, invasion, and migration, in addition to inducing apoptosis via Bax and enhancing caspase-3 expression, and decreasing the expression of Bcl-2." (PMID 36144625, 2022). "Furthermore, miR-15a and miR-16 were shown to act as tumor suppressors which inhibit cancer cell proliferation by targeting various cyclins and CDKs, and induce apoptosis through downregulation of the antiapoptotic gene Bcl-2." (PMID 35456001, 2022). "Furthermore, the overexpression of the Bcl-2 gene is positively correlated with anticancer drug resistance and efficacy of many clinically used anti-cancer drugs is decreased." (PMID 36431014, 2022). "The effect of compound 6 on the balance of Bcl2/Bax proteins in MCF7 cancer cells was investigated." (PMID 36092142, 2022). "Additionally, oleanolic acid as well as its isomer, ursolic acid, upregulated Bax and Caspase-9 genes and downregulated Bcl-2 in various cancer cells." (PMID 36077389, 2022). "The reduction of cancer size may be explained by the downregulation of Bcl2 and up-regulation of BAX, which leads to a shift in the Bcl2/BAX ratio towards a pro-apoptotic signal in 7b-treated group." (PMID 35164019, 2022). "Interestingly, we found a strong enrichment of BCL-2 protein levels in immune cells when compared to cancer and other stromal cells." (PMID 34754079, 2022).
cancer (continued). "In the hematopoietic system, senolytics, including inhibitors of antiapoptotic proteins, are currently being used in cancer treatment, guided mostly by the fact that cancer stem cells rely more on B cell lymphoma 2 (BCL-2) pathways for survival than do normal hematopoietic stem cells." (PMID 35426369, 2022). "Suppression of D-2-HG production by an mtIDH1/2 inhibitor may decrease the BCL2 dependency of IDH1/2mt cancer cells and instead facilitate resistance against venetoclax." (PMID 34967233, 2022). "Treatment with a glutathione synthesis inhibitor, buthionine sulfoximine (BSO), decreased glutathione levels and abolished Bcl-2-mediated cisplatin resistance, indicating that Bcl-2-mediated cisplatin resistance in cancer cells is dependent on increased glutathione production." (PMID 35011702, 2022). "Bcl-2 is a major antiapoptotic protein and is upregulated in cancers, whilst Bax is proapoptotic." (PMID 35204791, 2022). "The levels of Pan Kla and histones H3K9la and H3K56la in liver cancer were positively correlated with the expression of cancer malignancy markers (the stemness marker CD133, the proliferation marker BCL2, the cancer cell proliferation marker Ki67, and the glycolysis enzyme LDHA)." (PMID 36686771, 2022). "In addition, it was demonstrated that the anti-apoptotic protein Bcl2 is upregulated in SALL4 transgenic mice, causing more cancer cell survival." (PMID 36010677, 2022). "For instance, cancer prefers to express a high level of Bcl-2, a pro-survival molecule, as one mechanism to overcome mitochondria-mediated apoptotic death, which leads to the development of Bcl-2 inhibitors as one potential management strategy to treat cancers." (PMID 36611966, 2022). "Interestingly, it was reported that the activated IL-6/JAK2/STAT3 pathway can inhibit bax/bcl2 related caspase-dependent apoptosis, leading to the promotion of proliferation and metastasis of cancer cells." (PMID 36431925, 2022). "Bcl-2 and Mcl-1 are overexpressed in some cancer cells, particularly after treatment." (PMID 35745769, 2022). "Furthermore, berberine also noticeably enhanced apoptosis in cancer cells via activation of caspase-9 and -3 and induction of a higher ratio of Bax/Bcl-2 proteins." (PMID 36144625, 2022). "Clearly, the study explored the various potential mechanistic pathways that might explain the tumorgenesis and development of cancer through the estimation of apoptotic and inflammatory markers such as Bcl-2, Bax, IL-8 and TNF-α." (PMID 35203561, 2022). "Additionally, trichothecin-induced apoptosis downregulates the expression of Survivin, XIAP, Bcl-xL, Bcl-2, and cyclin D1 via abrogation of NF-κB activation in human cancer cells featuring constitutively active NF-κB." (PMID 35955813, 2022). "Vinorelbine has the competence to inhibit the migration and invasion of cancer cells, as well as induce G2/M arrest and cell apoptosis, which can be proved by the increase in Bax level and the decrease in Bcl-xL and Bcl-2 levels in H1975, HepG2, and HCT116 cells." (PMID 36104717, 2022). "Bcl-2 is a critical player in imparting resistance to cancer cells." (PMID 35402265, 2022). "Bax protein levels were significantly (p < 0.001) increased after treatment with azilsartan in MCF-7 and MDA-MB-231 cancer cells, compared to untreated cells; bcl2 levels were notably (p < 0.05, p < 0.01) decreased in MCF-7 and MDA-MB-231, respectively, compared to untreated cells." (PMID 36431925, 2022). "The Bcl-2 gene is overexpressed in a wide variety of human cancers." (PMID 36431014, 2022). "The potential of Bcl-2 inhibitors to treat various cancers has been established in recent years." (PMID 36309485, 2022). "As many traditional anti-cancer drugs act on the BCL-2/BAX pathway, any disruption of this target may increase resistance to chemotherapy and radiotherapy by elevating the threshold needed for cell death." (PMID 36291779, 2022).
cancer (continued). "PRKG2 inhibits the migration, invasion, and proliferation of cancer cells and activates CREB, which modulates anti-apoptotic genes, such as BCL2, which are overexpressed in the resistant group, thereby contributing to the survival of cancer cells in the resistant group." (PMID 36338974, 2022). "In this way, BCL-2 helps cancer progression by promoting the survival of altered cells." (PMID 36142875, 2022). "Additionally, numerous studies performed on different cancer cells have determined phosphonates and coumarin induce apoptosis in the cells, and they not only decreased Bcl-2 expression but also increased Bax in cancer cells." (PMID 35164019, 2022). "We focused on three genes that are associated with cancer: MAPKAPK2, ATF4, and BCL2." (PMID 36142475, 2022). "Thus, the expression of the Bcl-2 gene and protein represent a major therapeutic target for the design of anti-cancer drugs." (PMID 36431014, 2022). "This may indicate the need for dual targeting of both Bcl-2 and Bcl-XL to obtain the efficient decline in cancer cell viability." (PMID 35804872, 2022). "The spontaneously high expression of BCL2 in either model appears sufficiently high by itself for supporting the outgrowth of clonal malignant tumors without the need for promoter mutations." (PMID 36358756, 2022). "Downregulation of FN1 could increase the expression of the proapoptotic protein Bax and decrease the expression of the antiapoptotic protein Bcl-2 in cancer cells." (PMID 35370699, 2022). "In addition, in the past few decades, a lot of research has been done to find BCL-2 inhibitors for cancer treatment, but there are still some prospective drugs that stay at the cellular level and rarely establish animal models." (PMID 36313628, 2022). "The delivery of DOX and Bcl-2-siRNA simultaneously to an A2780/AD human ovarian cancer cells system, based on MSNs, could address the problem of multidrug resistance of the cancer cells." (PMID 36005484, 2022). "However, a recent study has revealed bcl-2 as a direct target for miR-1, although several other cancer-related pathways are also targeted." (PMID 35804872, 2022). "Defects in the physiological mechanisms of apoptosis may contribute to different human diseases like cancer, pro-apoptotic (Bax and cleaved caspase-3) and anti-apoptotic proteins (BCL-2) that play important roles in the regulation of cell death." (PMID 35470736, 2022). "Besides SMAD4 and DCC, this region encloses known cancer-related genes that were significantly associated with a higher relapse probability of early-stage primary tumors, namely SMAD2 and BCL2." (PMID 36085309, 2022). "The anti-apoptotic function of Bcl-2 in different types of human cancer has been well studied, and targeting of Bcl-2 may be a novel modality of cancer therapy." (PMID 34980181, 2022). "Lactate has been previously shown to protect cancer cells from glucose starvation via the AKT/mTORC/BCL-2 axis; therefore, the increased lactate and higher stimulation capacity of AKT may play protective roles in the IR-iPSCs." (PMID 35987697, 2022). "Targeting Bcl-2 specifically in the lamina propria of the cancer tissue could prove to be a potential therapeutic option." (PMID 36013602, 2022). "This could partly explain the heterogeneity/controversy between the observed prognostic signature of BCL2 in different cancer types, including CRC, in the present study and previous reports." (PMID 34994989, 2022).
cancer (continued). "Our in silico analysis revealed that miR‐497 and its target gene B‐cell lymphoma‐2 (BCL2) could be related to poor cancer outcomes." (PMID 34994989, 2022). "First, basal single-channel IP3R activity was acquired in the presence of 2 μmol/L or 5 μmol/L [IP3], followed by the addition of 1 μmol/L ABT-199, a concentration sufficient for binding Bcl-2 in several cancer cell lines with a lethal dose 50 (LD50) of about 10 nmol/L." (PMID 36045908, 2022). "ABT-737 is a cancer therapeutic agent that induces apoptosis by inhibiting Bcl-2/Bcl-xL." (PMID 35805049, 2022). "Accordingly, inhibition of the Bcl‐2‐triggered suppression of apoptosis is expected to be a promising therapeutic approach for patients with AML via inducing an effective programming of the death of cancer cells." (PMID 34173723, 2022). "On the other hand, JNK could induce cancer cell apoptosis by activating proapoptotic Bcl-2 proteins Bax and Bim that contribute to caspase-9 activation in the mitochondrial pathway." (PMID 38023774, 2022). "Moreover, a combination of imipridones with BCL‐2 inhibitors has shown promise for increased cancer cell apoptosis." (PMID 35929764, 2022). "Many small molecules that target Bcl-2 have been identified and used for cancer treatment." (PMID 36557977, 2022). "A high expression of Bcl-2 protein was found in many drug-resistant cancer cells." (PMID 35402265, 2022). "Genes of interest from the selected cancer‐related gene set, restricted to gene mutations occurring in >3 patients, revealed mutations in several genes previously reported in FL (e.g., CREBBP, BCL2, KMT2D)." (PMID 34791836, 2022). "Moreover, alteration of some other genes like Bax, Caspase3, Bcl-2 and iNOS affect the cancer’s progression." (PMID 36552412, 2022). "Enhanced expression of anti-apoptotic B-cell lymphoma 2 (BCL-2) protein is frequent in cancer." (PMID 35443750, 2022). "Moreover, another study reported that the Bcl-2 as an apoptotic marker was increased with the incidence of cancer, which is consistent with the present results." (PMID 35203561, 2022). "Discovering a potential molecule to inhibit Bcl2 may open a new door to cancer treatment.Stigmasterol (SS) is a member of phytosterols which can inhibit the progression of different cancers by decreasing the tumors' viability and promoting apoptosis." (PMID 35725497, 2022). "Both in vitro and in vivo studies have shown that elevated Bcl-2 level in cancer cells under hypoxia condition induces VEGF expression, enhances its mRNA stability, promotes its secretion and its transcriptional activity, resulting in increased vascularization that is independent of cell survival." (PMID 35056993, 2022). "Resisting cell death and preventing apoptosis is one of the hallmarks of cancer, and targeting therapy resistance through BCL-2 inhibition may be a potential successful therapeutic approach to induce apoptosis in AML cells." (PMID 35884517, 2022). "There was a considerable reduction in the mRNA expression of Bcl-2, which is an anti-apoptotic protein and a downstream molecule of the NF-κB pathway and variety of cancers exhibit a higher expression of Bcl-2 and confer resistance to the apoptotic effect of chemo- and radiotherapy." (PMID 35992866, 2022). "Bcl-2 over-expression has been proposed as one of the features of cancers." (PMID 35123593, 2022). "In our analysis, BCL2 was found in nine cancers and involved in five hallmarks." (PMID 36304266, 2022). "C-MYC and BCL2 oncogenes evidence parallel outcomes in cancer development." (PMID 35890188, 2022).
cancer (continued). "Overall, these data suggested that muscle atrophy in cancer cachexia was related to activation of apoptosis while GDF-15 might induce apoptosis in muscle tissues via activating Bcl-2/caspase-3 pathway." (PMID 35379793, 2022). "Additionally, it increased the expression of BAX and CASP3, and decreased the expression of the anti‐apoptotic gene of BCL‐2 in cancer cells." (PMID 36514755, 2022). "In both types of cancers, overexpression of miR-429 inhibits Bcl-2-mediated cell survival." (PMID 36158660, 2022). "Bcl-2 plays a pivotal role in cell survival/cell death signaling pathway in cancers." (PMID 35627200, 2022). "In cancer, oncogenes such as the pro-survival gene, BCL2, can escape NMD." (PMID 36552825, 2022). "Bcl-2 has induced cancer growth and resistance to chemotherapeutics in xenograft models of NSCLC." (PMID 35402265, 2022). "In light of those findings, it was speculated that NRMT may regulate the CENPA/Myc/Bcl2 axis to affect the chemoresistance in human cancers." (PMID 35013138, 2022). "With BCL-2 inhibitors proving effective against cancer and HIV-1, they could potentially be used as an “antiviral” against other viral species." (PMID 36569952, 2022). "Downregulating NF-κB and Bcl-2 proteins could be the possible reason for the induction of apoptosis in cancer cells." (PMID 35774603, 2022). "BCL2 is a key apoptosis regulator and is frequently upregulated in cancer cells." (PMID 35908280, 2022). "However, we and others have described multiple mechanisms of resistance to BCL-2 inhibition in different types of cancer, including B-cell lymphomas." (PMID 36167829, 2022). "However, the miR-15a/16-1 cluster is a frequently deleted region in B cell chronic lymphocytic leukemia (CLL) and other cancers, resulting in higher expression of BCL2 oncogene." (PMID 35645336, 2022). "Obviously, the expression level of BCL-2 protein in many cancer cells significantly increased." (PMID 36313628, 2022). "Patients with cancer who had elevated Bcl2 levels were radioresistant." (PMID 36139697, 2022). "Importantly, suramin-mediated inhibition of RNA binding increased the expression of miR-1-3p, and enhanced sensitivity of cancer cells to Bcl-2 inhibitor navitoclax treatment." (PMID 35804872, 2022). "CCl4-induced hepatotoxicity, on the other hand, exhibited apoptotic response declination by increasing BCL-2 (B-cell lymphoma-2) related putative X protein and downregulating apoptotic regulator BCL-2; thus, BCL-2 was demonstrated to be a key role on regulatory pathway in cancer development." (PMID 35313329, 2022). "Moreover, they found that peptides derived from Trichoplax Bcl-2 homologs can interact and inhibit human Bcl-2 proteins, sensitizing cancer cells to chemotherapy." (PMID 35883457, 2022). "Our study on the comparison of Bcl-2 and Bax expression in epithelial and lamina propria tissues in normal, low-grade and high-grade carcinoma showed a significant number of positive cells expressing the anti-apoptotic marker Bcl-2 in the lamina propria of all samples." (PMID 36013602, 2022). "Although Bcl-2 inhibition has an established apoptosis-inducing effect in normal cancer cells, targeted Bcl-2 inhibition alone may insufficiently trigger apoptosis in CSCs." (PMID 34063628, 2021). "Furthermore, studies have shown that overexpression of Bcl2 can make cancer cells more resistant to chemotherapy." (PMID 33652630, 2021). "To understand the molecular basis of this CVI-dependent anti-apoptotic effect we analyzed protein levels of two key opposing apoptosis regulators, the pro-apoptotic Bax and anti-apoptotic Bcl-2 proteins, which had been implicated previously in CVI-mediated effects in cancer cell lines." (PMID 34473704, 2021).